PAPPA2 (pappalysin 2)
Description:
Metalloproteinase which specifically cleaves insulin-like growth factor binding protein (IGFBP)-5 at the '163-Ser-|-Lys-164' bond. Shows limited proteolysis toward IGFBP-3.
Synonyms: PAPP-A2; PAPP-E; PLAC3; PAPPE; SSDA
Tractability: Antibody: its Gene Ontology location is reachable by antibodies, with high confidence; UniProt places it where antibodies can reach, with medium confidence; UniProt predicts a signal peptide or a membrane-spanning region.
Gene: Protein-coding gene on chromosome 1 (176,463,171 to 176,845,601, forward strand). Ensembl gene ENSG00000116183.
Subcellular location: Secreted
Subcellular location (Human Protein Atlas): Endoplasmic reticulum; Vesicles; Predicted to be secreted
Pathways (Reactome):
Metabolism of proteins: Regulation of Insulin-like Growth Factor (IGF) transport and uptake by Insulin-like Growth Factor Binding Proteins (IGFBPs)
Gene Ontology:
Molecular function: metalloendopeptidase activity; metallopeptidase activity; zinc ion binding
Biological process: proteolysis; cell surface receptor signaling pathway; regulation of cell growth; response to salt stress
Cellular component: extracellular exosome; extracellular region; apical plasma membrane
Genetic constraint (gnomAD): Loss-of-function variants: 80 observed, 175.62 expected, observed/expected ratio (o/e) 0.46, 90% interval 0.38 to 0.55. The upper end of that interval is the gene's LOEUF score, 0.55, which puts it in group 2 of 6, group 1 being the genes least tolerant of losing a copy. Missense variants: 2,024 observed, 2,306.5 expected, observed/expected ratio (o/e) 0.88, 90% interval 0.85 to 0.91. Synonymous variants: 789 observed, 878.66 expected, observed/expected ratio (o/e) 0.9, 90% interval 0.85 to 0.95.
Homologues: Orthologues: chimpanzee PAPPA2 (99% identical), macaque PAPPA2 (96% identical), pig PAPPA2 (84% identical), guinea pig PAPPA2 (80% identical), rat Pappa2 (79% identical), mouse Pappa2 (79% identical), rabbit PAPPA2 (77% identical), zebrafish pappa2 (48% identical), tropical clawed frog pappa2 (47% identical). Paralogues in human: PAPPA (40% identical), CSMD2 (12% identical), CSMD1 (11% identical), CSMD3 (11% identical), CFH (11% identical), SVEP1 (9% identical), CR1 (7% identical), C6 (7% identical), C7 (6% identical), SEZ6L (6% identical), CFHR5 (6% identical), F13B (5% identical), and 27 more.
Diseases named in the same sentence as PAPPA2 in open-access papers:
PAPPA2 is named in the same sentence as 53 diseases in open-access papers, as found by Europe PMC text mining. Sharing a sentence is not in itself a finding about the gene and the disease. The quoted sentences say what the papers report.
preeclampsia (14 papers, 2011 to 2024). Preeclampsia is a hypertensive disorder of pregnancy that is characterized by new-onset hypertension with proteinuria presenting after 20 weeks of gestation, and depending on mild or severe forms may initially present with severe headache, visual disturbances, and hyperreflexia. "Recent researches on PAPPA2, Pregnancy-Associated Plasma Protein A2, have provided new insights into its role in preeclampsia." (PMID 39544937, 2024). "To test this hypothesis, we deleted Pappa2 in a mouse model of preeclampsia and intrauterine growth restriction: deficiency of matrix metalloproteinase-9 (MMP9)." (PMID 29895300, 2018). "Five studies have shown that placental expression of pregnancy-associated plasma protein A2 (PAPPA2) is upregulated at delivery in preeclampsia or a complication of preeclampsia, HELLP (Hemolytic anemia, Elevated Liver enzymes, and Low Platelet count) syndrome." (PMID 21496272, 2011). "PAPPA2 has shown promise as a potential biomarker for predicting preeclampsia, with good classification performance in identifying women at risk." (PMID 39544937, 2024). "Functional enrichment analysis of the 447 human-upregulated DEGs, including ADAM12, ERVW-1, KISS1, LGALS13, PAPPA2, PGF, and SIGLEC6, revealed over-representation of genes implicated in preeclampsia and other pregnancy disorders." (PMID 34154587, 2021). "Severe early onset preeclampsia, fetal growth restriction, and HELLP syndrome were associated with high expression of PAPPA2 that encoded two circRNAs." (PMID 28842720, 2017). "Similarly, a CpG site in the promoter region of Pregnancy-Associated Plasma Protein A2 (PAPPA2), whose expression is elevated in preeclampsia and is a promising biomarker for its detection, exhibited reduced DNA methylation in preeclampsia samples compared to normal controls." (PMID 25247495, 2014). "We predicted that, if the elevated expression of PAPP-A2 in preeclampsia in humans reflects a compensatory response, then deletion of Pappa2 in mice would exacerbate effects of Mmp9 deletion, i.e., mice null for both Pappa2 and Mmp9 would show a more severe phenotype than mice null for Mmp9 only." (PMID 29895300, 2018). "Early placental development takes place in a low-oxygen environment, but impaired invasion into the decidua is thought to lead to even lower oxygen levels (hypoxia) in preeclampsia, which we hypothesize could upregulate PAPPA2." (PMID 21496272, 2011). "Notably, several HPGs associated with invasive EVTs (ADAM12, PAPPA2, PGF), and pregnancy complications such as preterm birth and preeclampsia (ADAM12, HSD17B1, KISS1, LGALS13, PAPPA2, SIGLEC6, ERVW-1), were found to be upregulated in human compared to rhesus placenta." (PMID 34154587, 2021). "It is not known whether altered PAPPA2 expression causes preeclampsia or is a response to placental pathology." (PMID 21496272, 2011). "In addition to PAPPA2, we also measured levels of PAPPA and ADAM12 since they are also placental IGFBP proteases associated with preeclampsia and intrauterine growth restriction (IUGR), and IGFBP proteases may be coregulated." (PMID 21496272, 2011). "Pregnancy-associated plasma protein A2 (PAPPA2) is an insulin-like growth factor-binding protein (IGFBP) protease expressed at high levels in the placenta and upregulated in pregnancies complicated by preeclampsia and HELLP (Hemolytic anemia, Elevated Liver enzymes, and Low Platelet count) syndrome." (PMID 21496272, 2011). "The biomarkers CGB5, LEP, LRRC1, PAPPA2, and SLC20A1 offer varying prospects for predicting preeclampsia." (PMID 39544937, 2024). "Interestingly, PAPPA2 deficiency in mouse models did not exacerbate intrauterine growth restriction, suggesting its upregulation in preeclampsia might not be a compensatory mechanism for impaired fetal growth." (PMID 39544937, 2024).
preeclampsia (continued). "Both these previous results and those of the present study are consistent with the hypothesis that PAPPA2 is upregulated as a consequence of placental pathology, rather than elevated PAPPA2 levels being a cause of abnormal placental development and preeclampsia." (PMID 21496272, 2011). "Whilst IGFBP4 and PAPPA2 were not on the list of validated proteins, the results are convincing given the plethora of data already available related to these proteins in preeclampsia, which are also aligned to our findings." (PMID 36351970, 2022). "In accordance with the altered trophoblast pathophysiology in early-onset preeclampsia, many of the most differentially regulated genes in women with preeclampsia (LEP, CGB, LHB, INHA, SIGLEC6, PAPPA2, and FLT1) have predominant or unique expression in the syncytiotrophoblasts." (PMID 24991435, 2014). "Furthermore, we could find only 5 genes (DAPK3, DUSP1, PAPPA2, ITCH, DENND2D) that overlapped with our gender-specific analysis of our data of all early and late combined preeclampsia samples." (PMID 25247495, 2014).
lung cancer (4 papers, 2020 to 2024). A malignant neoplasm involving the lung. "High expression of PAPPA2 is associated with mortality in lung cancer patients." (PMID 34222004, 2021). "Pappalysin 2 (PAPPA2) mutation, occurring most frequently in skin cutaneous melanoma (SKCM) and non‐small cell lung cancer (NSCLC), is found to be related to anti‐tumour immune response." (PMID 35811392, 2022). "PAPPA2 mutated most frequently in skin cutaneous melanoma (SKCM) and non‐small cell lung cancer (NSCLC) in the The Cancer Genome Atlas (TCGA) database." (PMID 35811392, 2022).
developmental dysplasia of the hip (3 papers, 2013 to 2021). A spectrum of hip abnormalities commonly presenting in infancy involving the relationship between the femoral head and the acetabulum and that includes subluxation or dislocation at rest or upon provocation. "In particular, we found changes in pelvic girdle shape, providing a potential explanation for the previously-reported associations between Pappa2 SNPs and developmental dysplasia of the hip in humans and birthing in cattle." (PMID 23457539, 2013). "Others have reported association between developmental dysplasia of the hip and a Pappa2 SNP in humans, again suggesting an effect of PAPP-A2 on bone shape." (PMID 23457539, 2013). "If similar functional variation in the Pappa2 gene exists in other species, effects of this variation on the shape of the pelvic girdle might explain the previously-reported associations between Pappa2 SNPs and developmental dysplasia of the hip in humans, and birthing in cattle." (PMID 23457539, 2013).
microcephaly (3 papers, 2016 to 2022). A congenital or acquired developmental disorder in which the circumference of the head is smaller than normal for the person's age and sex. "In particular, thin long bones associated with microcephaly are related to PAPPA2 mutations, while macrocephaly is characteristic of mutations activating FGFR-3." (PMID 35949366, 2022).
diabetes (2 papers, 2012 to 2017). "For example, high expression of Pla2g5 and/or Prl5a1, as well as low expression of Ankrd2 and/or Pappa2, indicates exposure to diabetes, while low expression of Kcnk2 and/or Mmp13 indicates exposure to breeder diet." (PMID 22701643, 2012).
gastric cancer (2 papers, 2021 to 2023). A primary or metastatic malignant neoplasm involving the stomach. "PAPPA2 is in relation to prognostic outcomes of gastric cancer together with immunes cells in the tumor microenvironment." (PMID 37124627, 2023). "In contrast, the expression of MKNK2 and PAPPA2 was significantly higher in paraneoplastic tissues than in gastric cancer tissues (Figures 15C1–F2)." (PMID 34222004, 2021). "The CGB5, MKNK2, and PAPPA2 genes may serve as important biomarkers for predicting the prognosis of gastric cancer." (PMID 34222004, 2021). "CGB5, MKNK2, and PAPPA2 may be used as novel prognostic biomarkers for gastric cancer." (PMID 34222004, 2021). "This study experimentally verified the levels of DNA repair-relevant genes, with higher levels of PAPPA2, MPO, MAGEA11, DEPP1, CPZ, and COLEC12 and lower level of CYTL1 in gastric cancer cells versus controls." (PMID 37124627, 2023). "In contrast to gastric mucosa epithelial cell line GES-1, transcriptional levels of PAPPA2, MPO, MAGEA11, DEPP1, CPZ, and COLEC12 were higher in gastric cancer cell lines HGC-27, MKN-28 and AGS, with lower transcriptional level of CYTL1." (PMID 37124627, 2023). "Higher levels of PAPPA2, MPO, MAGEA11, DEPP1, CPZ, and COLEC12 and lower level of CYTL1 were proven in gastric cancer cells versus controls." (PMID 37124627, 2023).
growth disorders (2 papers, 2023). "Previous studies suggested that PAPPA2 deficiency caused IGFBP regulation defects, leading to inefficient IGF-I bioavailability and longitudinal growth disorders." (PMID 37106701, 2023). "In addition, we found three new missense variants in PAPPA2, ADAM12 and EZH2, three genes related to growth disorders in different species including humans." (PMID 38017417, 2023).
HELLP syndrome (2 papers, 2017 to 2021). A life-threatening condition that can potentially complicate pregnancy. "Pappalysin 2 (PAPPA2) is a protein-encoding gene associated with several disorders, including Down’s syndrome and HELLP syndrome." (PMID 34222004, 2021).
Hip dysplasia (2 papers, 2013 to 2021). The presence of developmental dysplasia of the hip. "If similar functional variation in the Pappa2 gene exists in other species, effects of this variation on the shape of the pelvic girdle could potentially explain the previously-reported associations between SNPs in Pappa2 and pelvic bone-related phenotypes such as hip dysplasia and birthing ease." (PMID 23457539, 2013).
Hypertension (2 papers, 2010 to 2023). The presence of chronic increased pressure in the systemic arterial system. "Since PAPPA2 is expressed at high levels in the placenta, we predicted that altered PAPPA2 expression might influence placental development, but not necessarily the risk of hypertension." (PMID 20642865, 2010). "However, it is not clear whether PAPPA2 expression is upregulated to compensate for abnormal placentation or whether elevated PAPPA2 levels cause abnormal placental development, leading to hypertensive disorders." (PMID 20642865, 2010).
lung adenocarcinoma (2 papers, 2020 to 2022). A carcinoma that arises from the lung and is characterized by the presence of malignant glandular epithelial cells. "In 2013, a whole-exome sequencing study of lung adenocarcinoma patients identified PAPPA2 gene mutations that were associated with prolonged survival times." (PMID 32982990, 2020). "Obviously, there was no PFS or OS difference owing to PAPPA2 mutation in lung adenocarcinoma (LUAD), lung squamous carcinoma (LUSC), NSCLC or SKCM." (PMID 35811392, 2022).
pregnancy disorder (2 papers, 2015 to 2021). A disorder that is related to pregnancy. "A recent study showed PAPPA2 up-regulation in severe pre-eclampsia and, functionally, this may be mediated via increased placental hypoxia known to occur with this pregnancy disorder." (PMID 26161641, 2015).
breast carcinoma (1 paper, 2021).
gastric adenocarcinoma (1 paper, 2020). "To investigate whether gastrin directly affects PAPPA2 expression in CCK2R-expressing gastric epithelial cells, we used human gastric adenocarcinoma cells that have been stably transfected with the human CCK2 receptor (AGSGR)." (PMID 32004755, 2020).
gastric tumor (1 paper, 2020). "PAPPA2 is known to promote IGF signaling, a critical pathway involved in gastric tumor development." (PMID 32004755, 2020).
melanoma (1 paper, 2022). A malignant, usually aggressive tumor composed of atypical, neoplastic melanocytes. "Interestingly, 777T/I, 519L/F, and 1312G/R mutations on PAPPA2, and 231P/L and 171E/K mutations on CSMD3 were only observed in responders with melanoma or NSCLC." (PMID 36139377, 2022). "Furthermore, the reported TMB-related genes including PAPPA2, KALRN, and TTN were significantly correlated with patient response in NSCLC, which were also identified in melanoma." (PMID 36139377, 2022).
neuroendocrine tumor (1 paper, 2020). "However, PAPPA2 has not been associated previously with gastrointestinal disease, gastrin signaling, or neuroendocrine tumor development." (PMID 32004755, 2020).
osteoarthritis (1 paper, 2025). A noninflammatory degenerative joint disease occurring chiefly in older persons, characterized by degeneration of the articular cartilage, hypertrophy of bone at the margins and changes in the synovial membrane. "Several other genes are implicated in DDH but currently have a sparse association with human osteoarthritis in the literature, including BMS1, HOXD9, TBX4, TENM3, and PAPPA2." (PMID 41019141, 2025). "Several other genes implicated in DDH and/or FAI but with a sparse association with human osteoarthritis in the literature, including BMS1, HOXD9, TBX4, TENM3, PAPPA2, and HOXB9, should be further investigated to elucidate their role in osteoarthritis development." (PMID 41019141, 2025).
primary open-angle glaucoma (1 paper, 2026). "In this study, we reported a Chinese family that many members affected with primary open-angle glaucoma carried a PAPPA2 c.392G>C heterozygous mutation." (PMID 41993134, 2026).
sarcoma (1 paper, 2024). A usually aggressive malignant neoplasm of the soft tissue or bone. "Third, PAPPA2, encoding the IGFBP5-specific proteinase pappalysin 2, was among the recurrently mutated genes in FUS/EWSR1-TFCP2 sarcoma." (PMID 38168093, 2024).